TMPRSS2 (transmembrane serine protease 2)
Diseases named in the same sentence as TMPRSS2 in open-access papers (continued):
Sharing a sentence is not in itself a finding about the gene and the disease.
COVID-19 (continued). "Interestingly, TMPRSS2 is a directandrogen receptor target gene and its expression is increased by androgens in prostatecancer, which could also have an impact onTMPRSS2 expression in men with COVID-19." (PMID 32652001, 2020). "If TMPRSS2 is engaged in SARS-CoV-2 entry and ACE2 downregulation, TMPRSS2 inhibition would lead to COVID-19 prevention." (PMID 32604730, 2020). "Despite TMPRSS2 as well as ACE2 has higher expression levels after the onset of COVID-19 and cancers, no detailed study is available on their expression and interaction in cancer patients infected with COVID-19 or any other coronaviruses." (PMID 40055791, 2025). "Immunoaffinity isolation of uEVs from COVID-19 patients supported the notion that there was no co-clustering of ACE2 with TMPRSS2 at apical membranes from kidney or urinary tract epithelia." (PMID 39382598, 2025). "Moreover, studies of COVID-19 vaccine response in CF patients and possible precision medicine studies on ACE2/TMPRSS2 modulation should be conducted in the future." (PMID 40733537, 2025). "Studies have indicated that while camostat mesylate, a TMPRSS2 inhibitor, did not significantly improve clinical outcomes for hospitalized COVID-19 patients, it was related to decreased viral loads." (PMID 40297833, 2025). "In summary, we expect that SBTI, as a naturally derived trypsin inhibitor, has the potential to inhibit SARS-CoV-2 infection via ACE2, TMPRSS2, and CD147 pathways, which provides evidence for the development of a prospective functional food for COVID-19 therapy." (PMID 40724833, 2025). "These proteins are present in skin cells, with no statistical difference in TMPRSS2 expression between the COVID-19 and control groups." (PMID 40649826, 2025). "The connection between AR-regulated TMPRSS2 expression and SARS-CoV-2 entry has prompted investigations into whether ADT might confer protection against COVID-19 severity in prostate cancer patients, though results have been inconsistent." (PMID 41150771, 2025). "It remains uncertain whether the gastrointestinal symptoms observed in COVID-19 patients result from direct viral infection of the gastrointestinal tract, a process that may be exacerbated by altered expression of ACE2 or TMPRSS2." (PMID 41007801, 2025). "Interestingly, isolated uEVs from male patients with COVID-19 admitted to the hospital presented greater protein abundance of ACE2 and TMPRSS2 compared to control." (PMID 39382598, 2025). "Therefore, this study aimed to evaluate the expression levels of ACE2 and TMPRSS2 in nasopharyngeal samples before, during, and after SARS-CoV-2 infection, to understand the influence of these levels on the pathogenicity of COVID-19." (PMID 38606293, 2024). "Patients with COVID-19 with PRAD were observed to have a higher expression of TMPRSS2 compared to those without PRAD." (PMID 39057128, 2024). "Nevertheless, ACE2 and TMPRSS2 have crucial roles in SARS-CoV-2 infection well de-scribed in the literature, and their expression levels appear as a possible factor for the development of COVID-19 symptoms." (PMID 38606293, 2024). "The paradoxical decrease in testosterone levels with increased TMPRSS2 levels in patients with severe COVID-19 can potentially be secondary to negative feedback inhibition." (PMID 39449074, 2024). "Genetic variants could explain the variability in the clinical presentation of patients with COVID-19; some of them are found in ACE2, TMPRSS2, and the OAS family gene." (PMID 38673053, 2024). "Differences in COVID-19 clinical outcomes may be influenced by the level of expression of the SARS-CoV-2 entry receptor genes, ACE2 and TMPRSS2, in the airways." (PMID 39267977, 2024). "ACE is known as a functional receptor of SARS viruses including SARS-no-CoV2, and the severity of COVID-19 has been associated with the levels of ACE2 and TMPRSS2 co-expression and the proteinase activity of FURIN." (PMID 39273283, 2024).
COVID-19 (continued). "Furthermore, changes in the expression of the ACE2, TMPRSS2, CLEC4M and DPP4 genes, observed in TC, also occur in COVID-19." (PMID 39767735, 2024). "The findings revealed significant increases in the peripheral blood concentrations of ACE2 and TMPRSS2 in patients with non-severe COVID-19, compared to healthy individuals (P < 0.001 and P < 0.01, respectively)." (PMID 38444707, 2023). "We suggest that ACE2 and TMPRSS2 genes are not responsible for the “invulnerable” phenotype against COVID-19." (PMID 37700940, 2023). "These both enzymes (TMPRSS2 and ACE2) are considered as main points of cell-mediated viral entry, and several alkaloids are also being evaluated as drug inhibitors for these enzymes, and as novel drug strategies in COVID-19." (PMID 37287057, 2023). "The current study’s data revealed a significant increase in ACE2 and TMPRSS2 concentrations in the serum of both severe and non-severe COVID-19 patients compared to healthy subjects." (PMID 38444707, 2023). "In the current study, a correlation analysis was conducted between the concentrations of ACE2 and TMPRSS2 and the levels of circulatory miR-200b-3p and miR-214-3p in patients with severe and non-severe COVID-19." (PMID 38444707, 2023). "A GC-MS-based untargeted metabolomic analysis was used to profile the lipophilic compounds in the extracts followed by an in silico molecular docking analysis to examine the binding affinity of the compounds to anti-DM and anti-COVID-19 targets, e.g., α-amylase, α-glucosidase, ACE2, and TMPRSS2." (PMID 38132859, 2023). "In addition to inhibiting TMPRSS2, preventing the processing of the spike protein and cellular entry of SARS-CoV-2, AAT has a panoply of other activities that could antagonize both the intracellular virus and the multiple pathogenic mechanisms associated with severe COVID-19." (PMID 37294003, 2023). "Not surprisingly, the severity of COVID-19 has been associated with polymorphisms in ACE2, which promote Spike protein interactions, and in TMPRSS2 (transmembrane serine protease 2)." (PMID 38203577, 2023). "SARS-COV-2, or COVID-19, is a respiratory virus that enters tissues via the angiotensin-converting enzyme 2 (ACE2) receptor and is primed and activated by transmembrane protease, serine 2 (TMPRSS2)." (PMID 36656980, 2023). "Distribution of ACE-1 (rs4343), TMPRSS2 (rs12329760) and ACE-2 (rs908004) Alleles among severe and non-severe COVID-19 patients." (PMID 37426824, 2023). "In a randomized clinical trial of reduced expression of TMPRSS2 by antiandrogen therapies - degarelix did not result in amelioration of COVID-19 severity." (PMID 37007494, 2023). "The objective of this study was to explore the association between the serum levels of miR-200b-3p and miR-214-3p and the presence of circulating ACE2 and TMPRSS2 in severe and non-severe cases of COVID-19." (PMID 38444707, 2023). "Similarly, patients with severe COVID-19 exhibited higher serum levels of ACE2 and TMPRSS2 than healthy subjects (P < 0.0001)." (PMID 38444707, 2023). "Furthermore, disparities in gender infection of COVID-19 are suggested due to higher levels of ACE2 and TMPRSS2 in males, as well as hormonal influences on the immune response." (PMID 37287057, 2023). "Correlation analyses were conducted to assess the associations between the serum levels of miR-200b-3p, miR-214-3p, ACE2, and TMPRSS2 in patients with severe and non-severe COVID-19." (PMID 38444707, 2023). "In conclusion, the correlations of ACE2 and TMPRSS2 levels with either miR-200b-3p or miR-214-3p were not statistically significant in non-severe COVID-19 patients." (PMID 38444707, 2023). "During infection, COVID-19 targets two receptors, ACE-2 and TMPRSS2." (PMID 36979225, 2023). "This disparity in the severity and mortality of COVID-19 may be partially explained by sex-based variations in the expression of the ACE2 receptor and TMPRSS2." (PMID 37895256, 2023).
COVID-19 (continued). "Finally, we found that TMPRSS2 and CXCL10 are two putative biomarkers responsible for the increased vulnerability and fatality of prostate cancer patients to COVID-19." (PMID 36239108, 2022). "Molecular docking showed that N-0385 could block SARS-CoV-2 infection and treat COVID-19 by acting on ACE2, TMPRSS2 and NLRP3." (PMID 36329841, 2022). "Different clinical characteristics of COVID-19 in children and young adults compared to mature adults may be due to the different expressions of genetic components, such as ACE2 and TMPRSS2." (PMID 35207518, 2022). "Based on findings that A1AT can inhibit TMPRSS2, a repurposing of approved therapeutics such as Prolastin for SARS-CoV-2 infection has been proposed and entered a number of clinical trials for COVID-19." (PMID 36293378, 2022). "In a report from France, it was reported in autopsy studies that the hypothalamus is the target of COVID-19 by showing the excessive expression of angiotensin-converting enzyme 2 (ACE2) and transmembrane serine protease 2 (TMPRSS2) in the hypothalamus, especially in the paraventricular nucleus." (PMID 36016249, 2022). "Таким образом, эндокринная система обладает не только рецептором AПФ2, но и белком TMPRSS2, необходимым для доступа вириона SARS-CoV-2 к клеткам, что делает эндокринную систему особенно уязвимой как для разрушения, так и для изменения функции из-за COVID-19." (PMID 36337014, 2022). "In conclusion, this study shows an association of rs1799752/ACE1, rs1990760/IFIH1, rs2236757/IFNAR2, rs12329760/TMPRSS2, and rs2304256/TYK2 polymorphisms with worse COVID-19 outcomes, especially among female and non-white patients." (PMID 36672770, 2022). "Therefore, as a preventive strategy for COVID-19, there is an emerging need to develop drugs that target ACE2 and/or TMPRSS2." (PMID 35277472, 2022). "In a German case–control investigation, the CC genotype of TMPRSS2 rs383510 demonstrated relations, with a 1.73-fold greater risk of SARS-CoV-2 infection but not, however, with COVID-19 severity." (PMID 35193695, 2022). "However, the expression of ACE2 with other cofactors (TMPRSS2 -transmembrane serine protease-2 and Neuropilin-1) is still indecisive due to low concentrations of mRNA for ACE2 receptors in COVID-19 influenced patients." (PMID 35883527, 2022). "Thus, the designed peptidomimetic TMPRSS2 inhibitors prevent SARS-CoV-2 infection with comparable antiviral activity as CM, which is currently evaluated in clinical trials as COVID-19 therapeutic." (PMID 35804152, 2022). "Notably, CD, AD, TQ, and TQFL12 inhibited TMPRSS2 expression in cancer cell lines, including the PC3 prostate cancer cell line, implying a therapeutic role for preventing COVID-19 in cancer patients." (PMID 36364238, 2022). "This receptor also increases the expression of ACE-2 and inhibits the expression of a transmembrane serine protease (TMPRSS2) relevant for viral entry with ACE-2 internalization and could be a potential mechanism of 5-ASA favouring COVID-19." (PMID 36556155, 2022). "We first analysed the relation between TMPRSS2 rs12329760 and life-threatening SARS-CoV-2 infection in 2,244 critically ill, hospitalized, COVID-19 positive patients from 208 UK intensive care units (ICUs) recruited as part of the GenOMICC (genomicc.org) and ISARIC 4C (isaric4c.net) projects." (PMID 35104687, 2022). "Study of expression patterns of ACE2 and TMPRSS2 genes during PMV and AKI could be important in understanding the pathogenesis of COVID-19 in critically ill patients." (PMID 35123426, 2022). "We hypothesize that interplay of ACE2/ADAM17/TMPRSS2 and CD146 in the kidney may lead to sex differences in CKD as well as in COVID-19 by their sex differential expression and pathways." (PMID 35887687, 2022). "Contingency tables for TMPRSS2 genotype in the noninfected close-contact group and the infected groups classified by severity of COVID-19." (PMID 36532428, 2022).
COVID-19 (continued). "This compound is an effective inhibitor of coronavirus entry into host cells through the endocytic pathway, however because of its lack of effect on the TMPRSS2-mediated pathway, chloroquine has been shown to be ineffective to treat COVID-19 patients." (PMID 35587469, 2022). "Clinical and pre-clinical studies demonstrated that RAAS-blocking agents can be safely used during a SARS-CoV-2 infection but it is unknown if DPP-4 inhibitors or SGLT2-blockers may promote COVID-19 by increasing the host viral entry enzymes ACE2 and TMPRSS2." (PMID 35331159, 2022). "Analysis of CNAs in TMPRSS2 and CXCL10 may help in assessing the clinical features of COVID-19 patients with aggressive or indolent prostate cancer." (PMID 36239108, 2022). "Among the drugs that strongly inhibit TMPRSS2, nafamostat mesylate has the strongest antiviral effect against COVID-19, and its IC50 value is approximately 600 times higher than that of remdesivir, the standard treatment for COVID-19." (PMID 35745792, 2022). "Since AAT irreversibly inhibits serine proteases and elastases, but may also exert anti-viral, anti-TMPRSS-2, anti-inflammatory, anti-thrombin, anti-NETs and antiapoptotic activities, AAT represents an additional candidate for the treatment of COVID-19." (PMID 35163482, 2022). "In sum, none of the TMPRSS2 inhibitors clearly curbed SARS-CoV-2 infection or mitigated the progression of COVID-19." (PMID 35163273, 2022). "We therefore speculate that the sex difference in both COVID-19 and CKD may be brought about by the androgen stimulated Tmprss2-ERG fusion transcript." (PMID 35887687, 2022). "In COVID-19, SARS-CoV-2 infection depends the host cell factors ACE2 and TMPRSS2." (PMID 33743807, 2021). "Our data also supports that TMPRSS2 effect on modelling disease severity may be dependent on ACE2 levels, suggesting that the impact of this serine protease on COVID-19 might be better explored in combination to its partner ACE2." (PMID 33958627, 2021). "We used the following keywords: COVID-19, SARS-CoV-2, smoking, ACE2, TMPRSS2, furin, and treatment." (PMID 33777332, 2021). "Pulmonary TMPRSS2 regulation appears not to account for the sex-discordance in COVID-19 clinical outcomes." (PMID 34045511, 2021). "Camostat mesylate, a protease inhibitor that prevents proteolytic priming of SARS-CoV-2 spike protein by TMPRSS2 to enable ACE2 binding, is still under investigation as an intervention for COVID-19 (ClinicalTrials.gov Identifiers NCT04353284, NCT04524663, NCT04470544, and others)." (PMID 33919584, 2021). "However, a small fraction of circulating immune cells (including dendritic cells, monocytes, T cells) in the PBMC of COVID-19 patients express ACE2 and TMPRSS2." (PMID 34578338, 2021). "Our work suggests that sex differences in COVID-19 outcomes attributable to viral entry are independent of TMPRSS2." (PMID 34045511, 2021). "The main genes, which included in COVID-19 entrance, are ACE2 and TMPRSS2." (PMID 34366659, 2021). "Collectively, these endogenous molecules such as ACE2, TMPRSS2, and furin were essential for SARS-CoV-2 infection, which could serve as potential targets for the treatment of COVID-19." (PMID 33987176, 2021). "The effect of DM on the expression of myocardial TMPRSS2 protein levels was next investigated in the explanted heart from non-COVID-19 failing heart DM and Non-DM patients." (PMID 33962629, 2021). "Another clinically approved TMPRSS2 inhibitor, nafamostat, requires intravenous dosing and has also shown effect SARS-CoV-2 in vitro, but there isn’t any clinical study about the effectiveness of nafamostat for treating COVID-19 at the moment." (PMID 34391321, 2021). "We found that the expression level of placental ACE2, but not TMPRSS2 or Furin, was higher in women with severe COVID-19." (PMID 34257394, 2021).
COVID-19 (continued). "In the pooled COVID-19 patients, ACE2 was expressed in several immune cells, such as dendritic cells, CD14 monocytes, CD4 memory T cells, CD4 naive T cells, CD8 effector T cells, etc.; TMPRSS2 was expressed in most immune cells." (PMID 34578338, 2021). "SARS-CoV-2 antisense RNA could also be found in stromal cells of the ovary in one COVID-19 patient, where ACE2 RNA was also mainly expressed, and some stromal cells expressed TMPRSS2 RNA." (PMID 34440669, 2021). "COVID-19 myocardial tissue from DM patients showed a more pronounced TMPRSS2 protein expression level compared to Non-DM (p < 0.01)." (PMID 33962629, 2021). "The CC genotype of TMPRSS2 rs383510 was associated with a 1.73-fold increased SARS-CoV-2 infection risk, but was not correlated to severity of COVID-19." (PMID 33968142, 2021). "Additionally, a smaller number of biopsies (COVID-19 n = 5, controls n = 6) were analyzed for the expression of ACE2 and TMPRSS2 as mediators of virus entry as well as for the expression of EpCAM, CD8α, CD31, and CD163." (PMID 34420043, 2021). "This similarly suggests a need to define SARS-CoV-2 penetration susceptible cells as cells bearing a SARS-CoV-2 penetration disposition where in this case the functional receptor material base is TMPRSS2, also imported to IDO-COVID-19 from the Protein Ontology." (PMID 34275487, 2021). "Therefore, the expression of ACE2 and TMPRSS2 directly points to the cellular tropism of SARS-CoV-2, which has important implications for the pathogenesis of COVID-19." (PMID 34094637, 2021). "Based on the available literature, COVID-19 outcomes vary from mild to severe clinical manifestations and this may reflect different airway levels of ACE 2 and TMPRSS2, which are indispensable for virus entry into the host cell." (PMID 33996694, 2021). "TMPRSS2 is an enzyme that primes the spike S protein of the SARS-CoV-2 virus to promote virus entry, IL6 and TNF are pro-inflammatory cytokines that are found generally elevated in severe COVID-19 patients." (PMID 34109284, 2021). "The authors reported that both ACE2 and TMPRSS2 mRNA and protein were not substantially expressed in the conjunctival samples and thus suggested that COVID-19 transmission via this pathway would be unlikely." (PMID 33710758, 2021). "Since testosterone/AR signaling is reduced during aging and its reduction is associated with COVID-19 death incidence in men, testosterone therapy may be useful for boosting TMPRSS2/ACE2 signaling, and thereby reducing COVID-19 death incidence." (PMID 34832534, 2021). "Future studies assessing the roles of nasopharyngeal ACE2 and TMPRSS2 in SARS-CoV-2 infection and COVID-19 disease severity should include a larger number of random family clusters that include symptomatic patients, as well as those with different levels of severity." (PMID 34730438, 2021). "Smoking has been shown to enhance the expression of the angiotensin-converting enzyme-2 (ACE-2) and transmembrane serine protease 2 (TMPRSS2) key entry genes utilized by SARS-CoV-2 to infect cells and induce a ‘cytokine storm’, which further increases the severity of COVID-19 clinical course." (PMID 33777332, 2021). "Interestingly, except for FURIN, the expression level of ACE2, TMPRSS2, and NRP1 were significantly dysregulated in nasal tissues from COVID-19 positive patients." (PMID 33732102, 2021). "Taking into account these findings along with the potential novel treatments for COVID-19, such as manipulation of ACE2 receptor, the existing data on TMPRSS2-targeted treatments can be considered as a promising route of therapeutics that can be further investigated." (PMID 32992681, 2020). "We demonstrate that ACE2 and TMPRSS2 are colocalized in adrenocortical cells, and that the cortisol levels are lower in critically ill patients with COVID-19 as compared to those of non-COVID-19 critically ill patients." (PMID 33488517, 2020).